TRPC4 (transient receptor potential cation channel subfamily C member 4)
Diseases named in the same sentence as TRPC4 in open-access papers (continued):
Sharing a sentence is not in itself a finding about the gene and the disease.
pulmonary hypertension (4 papers, 2018 to 2023). Increased pressure within the pulmonary circulation due to lung or heart disorder. "Recent reports suggest that TRPC4 channels are implicated in (bacterial toxin-induced/aggravated) pulmonary arterial hypertension/stenosis by increasing proliferation/permeability of endothelial and smooth muscle cells." (PMID 29865154, 2018). "TRPC4 involvement in pulmonary hypertension is noted, especially in the smooth muscle cells of the pulmonary artery." (PMID 38025430, 2023). "Recent studies have shown that TRPC4 participates in pulmonary hypertension by affecting the proliferation of endothelial cells and smooth muscle cells." (PMID 34899056, 2021). "In another ovine model with partial gestation under chronic hypoxia, the newborn lambs show pulmonary hypertension that persists at sea level and increased TRPC4 and Orai1 expression." (PMID 29867539, 2018). "TRPC4 channels have been studied in the development of pulmonary hypertension." (PMID 29865154, 2018). "However, TRPC1/4/5 channels have been implicated in various human diseases, including seizures (TRPC5 and TRPC1:C4), fear-related behaviour (TRPC5), severe pulmonary arterial hypertension (TRPC4), heart failure (TRPC1/C4), and chemotherapeutic resistance of cancers (TRPC5)." (PMID 29865154, 2018). "Moreover, chronically hypoxic newborn lambs gestated and born at 3,600 m altitude, have pulmonary hypertension, increased HPV, and upregulated TRPC4 and Stim1 pulmonary transcripts." (PMID 29867539, 2018).
renal cell carcinoma (4 papers, 2015 to 2021). "By contrast, TRPC4 has been shown to inhibit the proliferation of renal cell carcinoma cells, after the cells were exposed to englerin A (an anti-cancer substance, found in the bark of the Phyllanthus engleri tree)." (PMID 36046118, 2021). "Previous studies have suggested that A498 renal cell carcinoma cells contain endogenous EA-activated TRPC1/TRPC4 heteromeric channels." (PMID 28325835, 2017). "TRPC4-downregulation has been proposed as a trigger for tumor angiogenesis in renal cell carcinoma." (PMID 36046118, 2021). "Englerin A sensitive A-498 renal cell carcinoma cells were transfected with TRPC4 siRNAs to determine whether TRPC4 mRNA knockdown affects the cell’s response to englerin A. Two different siRNAs reduced TRPC4 mRNA levels by over 80% relative to a non-targeting control siRNA." (PMID 26098886, 2015). "In renal cell carcinoma (RCC), A498 RCC cell lines responded to englerin A by elevation of intracellular Ca2+ levels and followed by cell death The Ca2+ entry was due to activation of TRPC4 channels, as was demonstrated by patch-clamp studies." (PMID 32046188, 2020).
synovial sarcoma (4 papers, 2017 to 2020). "Based on the result of our study, we propose that heteromeric TRPC4/C1 is a primary target of EA for a potent anti-human synovial sarcoma cell effect mediated via Na+ loading caused by sustained channel activation coupled with insufficient compensation by Na+/K+-ATPase." (PMID 29209034, 2017). "In contrast, the activation of Ca2+ permeable TRPC4 channel reduced cell proliferation in a Ca2+-independent manner, in the human synovial sarcoma." (PMID 31597314, 2019). "We conclude that EA has a potent cytotoxic effect on human synovial sarcoma cells which is mediated by heteromeric TRPC4/C1 channels and Na+ loading." (PMID 29209034, 2017). "Our recent study has demonstrated that the activation of heteromeric TRPC4 and TRPC1 (TRPC4/C1) causes a potent cytotoxic effect on SW982 cells mediated via Na+ loading, suggesting that heteromeric TRPC4/C1 is a promising target of anti-tumor agents against synovial sarcoma." (PMID 29757938, 2018).
migraine (3 papers, 2021 to 2024). "We found that TRPC4 is highly expressed in TG neurons and that inhibiting TRPC4 can prevent migraine-linked cutaneous mechanical hypersensitivity and reduce CGRP plasma levels in a mouse model of migraine." (PMID 37175602, 2023). "A recent study showed that TRPC4 is highly expressed in TG neurons and that pharmacological inhibition of TRPC4 significantly prevented migraine-linked cutaneous mechanical hypersensitivity and increased plasma levels of CGRP." (PMID 37175602, 2023). "Here, we have shown that TRPC4 is highly expressed in cutaneous peptidergic sensory neurons in the trigeminal ganglia, a key structure implicated in the generation of migraine." (PMID 34790097, 2021). "To explore the mechanisms by which daily TRPC4 inhibition attenuates pain hypersensitivity, we examined transcriptional changes in several neuropeptides enriched in primary sensory neurons and/or previously associated with migraine." (PMID 34790097, 2021). "However, we have previously shown that TRPC4 is associated with serotonergic signaling in peptidergic neurons and various studies have implicated serotonin in the pathogenesis of migraine." (PMID 34790097, 2021). "Apart from these, TRPC4 is another subtype of TRP channels that have been implicated in pain and migraine." (PMID 37175602, 2023). "This suggests that TRPC4 inhibition can potentially be used as anti-migraine pain therapy in both men and women." (PMID 34790097, 2021). "In this study, we characterized the role of TRPC4 in pain and evaluated its inhibition as anti-migraine pain therapy in preclinical mouse models." (PMID 34790097, 2021). "Here, we used a combination of behavioral, cellular, and biochemical approaches to reveal the function and therapeutic value of targeting TRPC4 in the NTG-induced animal model of migraine." (PMID 34790097, 2021). "Targeting TRP channels holds great promise for pain treatment, and we anticipate that strategies targeting TRPC4 in peripheral sensory neurons will be beneficial in treating migraine." (PMID 34790097, 2021). "The activation and role of amygdaloid TRPC4/TRPC5 in migraine should be further explored in future studies." (PMID 34790097, 2021). "To investigate whether TRPC4 plays a role in migraine, we used mouse models of migraine induced by intraperitoneal administration of nitroglycerin (NTG)." (PMID 37175602, 2023). "Thus, targeting TRP channels, including TRPC4, represents a promising approach for the prevention and treatment of migraine, a debilitating neurological disorder that affects millions of people worldwide." (PMID 37175602, 2023). "This review discusses the role and mechanisms of nociceptive neurons in migraine, the challenges of current anti-migraine drugs, and the evidence for well-studied and emerging TRP channels, particularly TRPC4, as novel targets for migraine prevention and treatment." (PMID 37175602, 2023). "Since TRPC4 is expressed in human DRG tissue and TRPC4/5 has entered clinical trials for the treatment of central nervous system disorders, it is possible that TRPC4 antagonists may soon be useful in migraine treatment." (PMID 37175602, 2023). "Because of the high expression of TRPC4 in trigeminal ganglia and colocalization with CGRP, we hypothesized that TRPC4 may play a role in migraine." (PMID 34790097, 2021). "To test whether TRPC4 inhibition can achieve analgesic effect in migraine, we used systemic injections of NTG in mice." (PMID 34790097, 2021). "Indeed, we further demonstrated that pharmacological inhibition of TRPC4 significantly prevented NTG-evoked cutaneous mechanical hypersensitivity and increased plasma levels of migraine-linked neuropeptide CGRP." (PMID 34790097, 2021). "In this study, we did not identify the endogenous agonists of TRPC4 that may be associated with migraine." (PMID 34790097, 2021).
migraine (continued). "Other TRP channels, such as TRPV4, TRPM3, TRPC4 and TRPM8, remain reliable candidates to be involved in migraine pain signaling with potential to be drug targets." (PMID 38221631, 2024). "Recently, we have demonstrated the role of transient receptor potential cation channel subfamily C member 4 (TRPC4) in itch and the modulation of the calcitonin gene-related peptide (CGRP), a biomarker and emerging therapeutic target for migraine." (PMID 34790097, 2021). "Collectively, our findings identify TRPC4 in peripheral sensory neurons as a mediator of CGRP release and NTG-evoked migraine." (PMID 34790097, 2021). "This suggests that TRPC4, via its expression in primary sensory neurons and regulation of CGRP, may represent a novel therapeutic target for migraine." (PMID 37175602, 2023). "TRPC4 via its expression in primary sensory neurons and regulation of CGRP may represent a novel therapeutic target for migraine." (PMID 34790097, 2021). "Second, we demonstrated that the small-molecule inhibitor ML204, a specific TRPC4 antagonist, significantly reduced episodic and chronic migraine-like behaviors in male and female mice after injection of nitroglycerin (NTG), a well-known migraine inducer in rodents and humans." (PMID 34790097, 2021).
prostate carcinoma (3 papers, 2009 to 2025). A carcinoma that arises from epithelial cells of the prostate gland. "A literature published in 2019 suggests that TRPC4 can be used as an independent influencing factor to determine the risk of recurrence after radical prostate cancer surgery: high expression of TRPC4 is associated with a lower risk of recurrence." (PMID 38818039, 2024). "Copy number alterations were also observed rarely with the exception of the amplification of TRPA1, which was amplified in 7.2% of prostate cancers in TCGA, and of TRPC4 and TRPC3, which were homodeleted in 5.9% and 2.5% of cases, respectively." (PMID 40332161, 2025). "The role of TRPC4 in tumor biological activities is a current research hotspot, and research in prostate cancer still needs to be further expanded." (PMID 38818039, 2024). "Similarly, in the MSK cohort, TRPA1 was amplified in 6.3% of prostate cancers and TRPC4 and TRPC3 were homodeleted in 4.4% and 1.5% of cases, respectively." (PMID 40332161, 2025). "In addition, the three target genes (DTNA, GJB1, and TRPC4) we searched for are also expected to be used for prostate cancer diagnosis and treatment in the future." (PMID 38818039, 2024).
renal carcinoma (3 papers, 2018 to 2020). A carcinoma arising from the epithelium of the renal parenchyma or the renal pelvis. "Therefore, pharmacological activation of TRPC4 by englerin A inhibits growth of A-498 and A-673 cells, suggesting that TRPC4 plays a tumour suppressor activity in renal cancer." (PMID 32575381, 2020). "The roles of TRPC4 and TRPC5 in migration/proliferation of cancer cells, angiogenesis, cancer cell multi-drug resistance and (−)EA-induced renal cancer cell death have been reviewed in 2016." (PMID 29865154, 2018). "Additionally, 100 μM histamine transiently activated currents with an outwardly rectifying I/V curve in the renal cancer A498 cells, which express TRPC1 and TRPC4." (PMID 30108272, 2018).
autism spectrum disorder (2 papers, 2022 to 2023). A spectrum of developmental disorders that includes autism, and Asperger syndrome. "This is consistent with a role for Trpc4 in regulating astrocyte calcium signaling in other autism spectrum disorders." (PMID 36524414, 2022). "In summary, our study has revealed the involvement of four known genes (DEAF1, CLCN3, KMT2C, and DHX30) as well as two novel genes (TRPC4 and SCFD2) in autism spectrum disorder across six families from Qatar." (PMID 38025430, 2023).
Cerebral ischemia (2 papers, 2014 to 2020). Restriction of arterial blood supply to the brain associated with insufficient oxygenation to support the metabolic requirements of the tissue. "Given that among the major brain TRPC isoforms, only TRPC4 has not been evaluated for its role in ischemic stroke, we then set out to compare brain damages caused by cerebral ischemia/reperfusion in wild type and TRPC4 knockout mice." (PMID 33490083, 2020). "TRPC4 is also shown to have a role in acute and delayed neuronal injury in focal cerebral ischemia, suggesting that TRPC4 could be a viable target, and its inhibition could protect against cerebral ischemia." (PMID 24852263, 2014). "We provide our own data showing that TRPC1/C4/C5, especially TRPC4, may be generally detrimental in OGD and cerebral ischemia/reperfusion." (PMID 33490083, 2020).
Constipation (2 papers, 2022 to 2024). Infrequent or difficult evacuation of feces. "In this study, we report on the inhibitory effect of the TRPC4 current by TCAs underlying the causality of colonic motility for TCA‐induced constipation using human and murine colons." (PMID 35560982, 2022). "Herein, we investigated whether TCA modulates TRPC4 channel activity and which mechanism in colonic myocytes consequently causes constipation." (PMID 35560982, 2022). "Although our experiments were confined to distinguishing sections of the murine colon, the identification of TRPC4 as a target protein involved in mass motility suggests a potential therapeutic mechanism for patients with constipation." (PMID 39458968, 2024). "Thus, TRPC4 seems to be a reasonable candidate as a molecular target of TCA‐induced constipation and IBS treatment with TCA." (PMID 35560982, 2022).
endometriosis (2 papers, 2018 to 2020). The growth of functional endometrial tissue in anatomic sites outside the uterine body. "Moreover, these channels were previously discovered to be somehow involved in several processes that regarded pathogenesis of endometriosis: TRPC1, TRPC4, and TRPV2 are involved in cell migration; TRPC4 in cell adhesion; and TRPM4, TRPM7, and TRPV2 have a crucial role in cell proliferation." (PMID 32046116, 2020).
glioma (2 papers, 2022 to 2024). A benign or malignant brain and spinal cord tumor that arises from glial cells (astrocytes, oligodendrocytes, ependymal cells). "Among the eight final identified hub genes, higher expression levels of TRPC1, TRPC3, and TRPC5 were significantly associated with longer OS time in glioma, while higher expression levels of TRPC4, TRPC6, MCOLN1, MCOLN2, MCOLN3 were significantly associated with shorter OS time." (PMID 35625048, 2022). "Higher levels of TRPC4, TRPC6, MCOLN1, MCOLN2, and MCOLN3 were significantly associated with shorter OS times in glioma." (PMID 35625048, 2022). "Besides, the upregulation of TRPC1 and TRPC4 in IDH1mt‐R132H glioma cells." (PMID 39189437, 2024). "The results of the spheroid model showed that the genes TRPC3, TRPC4, TRPC5, and TRPV1 were upregulated in glioma cells either wild‐type isocitrate dehydrogenase 1 (IDH1) or the IDH1 R132H mutant, with or without NaCl treatment." (PMID 39189437, 2024). "The gene expression levels of TRPC1, TRPC3, and TRPC5 were significantly higher in low-grade glioma (LGG), while the levels of TRPC4, TRPC6, TRPM7, MCOLN1, MCOLN2, and MCOLN3 were significantly higher in high-grade glioma (HGG)." (PMID 35625048, 2022). "However, the expression of TRPC4 in glioma presented no statistical significance." (PMID 35625048, 2022).
head and neck cancer (2 papers, 2017 to 2023). A primary or metastatic malignant neoplasm affecting the head and neck. "TRPC4 was found to be closely associated with incidence of head and neck cancer and poor survival of patients with kidney cancer." (PMID 36674553, 2023).
injury (2 papers, 2023 to 2025). Damage inflicted on the body as the direct or indirect result of an external force, with or without disruption of structural continuity. "Collectively, these results clearly demonstrated that TRPC4 is essential in the generation and maintenance of pain sensations after nerve injury, and its specific pharmacological modulators hold promise as therapeutic agents." (PMID 40202077, 2025).
ischaemic stroke (2 papers, 2020 to 2022). "In contrast to the rich information on TRPC6, little is known about the roles of TRPC4 and TRPC5 in brain injury associated with ischemic stroke." (PMID 33490083, 2020). "A role for TRPC4 has not been implicated CSVD; however, it has been found to play a role in regulating blood–brain barrier function and is hypothesised to be crucial for oedema formation in ischaemic stroke." (PMID 36175824, 2022).
ischemia (2 papers, 2020 to 2023). A hypoperfusion of the BLOOD through an organ or tissue caused by a PATHOLOGIC CONSTRICTION or obstruction of its BLOOD VESSELS, or an absence of BLOOD CIRCULATION. "Infarct areas were markedly smaller in the brain of TRPC4−/− mice than those in wild‐type (WT) mice, especially with a shorter period of ischemia." (PMID 36527242, 2023). "We found that the infarct areas were markedly smaller in brains of Trpc4–/– mice than wild type animals, especially with shorter time of ischemia, i.e., 30 and 90 min." (PMID 33490083, 2020). "In particular, 30 min of ischemia followed by 24 h of reperfusion resulted in scarcely detectable infarct areas in TRPC4−/− brains, while they were readily visible in WT specimens; however, the protective effect of TRPC4 was attenuated after prolonged ischemia (120 min)." (PMID 36527242, 2023). "Given that TRPC1 and TRPC6 may play some neuroprotective function during ischemia/reperfusion, it is plausible that the detrimental actions are mainly mediated by TRPC4 and/or TRPC5, and these two TRPC isoforms may dominate the cortical neuronal responses to ischemic insults." (PMID 33490083, 2020).
kidney cancer (2 papers, 2023). Primary or metastatic malignant neoplasm involving the kidney. "The small molecule AC1903, also known as A498, has been shown to inhibit several TRPC channels, including endogenous TRPC1:C4 channels, TRPC3, TRPC4, TRPC5, TRPC6, TRPC4-C1, and TRPC5-C1 in A498 kidney cancer cells." (PMID 36979640, 2023).
malignant melanoma (2 papers, 2023 to 2025). "While the precise role of TRPC4 in melanoma remains to be fully elucidated, its consistent presence across multiple skin cancer types indicates involvement in calcium-mediated processes such as cell migration and invasion." (PMID 40869148, 2025). "This is the first study to investigate the expression profiles of TRPC4 in common skin cancers such as basal cell carcinoma (BCC), squamous cell carcinoma (SCC), malignant melanoma (MM) and nevus cell nevi (NCN)." (PMID 36674553, 2023). "In this study, we investigate for the first time the expressions of proton-sensitive TRPC4 in basal cell carcinoma (BCC), squamous cell carcinoma (SCC), malignant melanoma (MM) and in nevus cell nevi (NCN)." (PMID 36674553, 2023).
ovarian carcinoma (2 papers, 2013 to 2023). A malignant neoplasm originating from the surface ovarian epithelium. "The two TRPC1 bands in the gel were α and β isoforms, and the bands for TRPC4 were α, β, γ and δ isoforms, respectively, as we described in ovarian cancer cells." (PMID 23840757, 2013). "The overexpression of TRPC4 increased ovarian cancer cell colony growth." (PMID 36674553, 2023). "Moreover, the alternative spliced variants may also contribute to the functionality of TRPC channels, such as TRPC1 and TRPC4 spliced isoforms in ovarian cancer SKOV3 cells." (PMID 23840757, 2013).